CCL2 (C-C motif chemokine ligand 2)
Diseases named in the same sentence as CCL2 in open-access papers (continued):
Sharing a sentence is not in itself a finding about the gene and the disease.
glioma (continued). "After migrating into the glioma environment, TAMs tend to possess the M2 phenotype, and their differentiation is driven by the secretion of immunosuppressive factors, including CSF-1, CCL2, IL-4, IL-6, IL-10, and transforming growth factor (TGF- β), from tumor cells." (PMID 30619286, 2018). "Therefore, we speculated that the increased expression of CCL2 could promote glioma aggressiveness through the pathway of chemokine signaling." (PMID 27716259, 2016). "CEBPB might act in glioma by regulating CCL2, CCND1, THBS1, THBS2, SMAD5, SMAD6, TGFBR2, and TCF12." (PMID 27716259, 2016). "Next we examined whether CCL2 is upregulated by IL1β treatment in cultured glioma cells." (PMID 25987130, 2015). "As expected, the conditioned medium from either GL261 or ALTS1C1 glioma cells significantly activated BV2 cells with a notable increase in pro-inflammatory cytokines, including IL-6, CCL-2, CXCL-10, MMP-14, TNFα, IL-1β, and iNOS." (PMID 41367876, 2025). "We will further explore the specific mechanisms by which Fn upregulates cytokines such as CCL2, CXCL1, and CXCL2 to promote glioma development in future studies." (PMID 39660865, 2025). "In glioma, MEX3A upregulates CCL2, a chemokine known to support proliferation, angiogenesis, and immune evasion, leading to alteration of the tumor microenvironment (TME) and promoting tumorigenesis." (PMID 40958871, 2025). "We found Fn promotes glioma proliferation and upregulates CCL2, CXCL1, and CXCL2 levels in vivo and in vitro models of glioma." (PMID 39660865, 2025). "Studies have found that glioma cells express many factors related to the proliferation of MDSCs (IL-6, IL-10, VEGF, PGE-2, GM-CSF, and TGF-β2); however, blocking the chemokine CCL2 signaling pathway in glioma cells effectively reduces the recruitment of MDSCs." (PMID 39206155, 2024). "Glioma cell-secreted soluble molecules, such as (C-C) motif ligand 22 (CCL22) or (C-C) motif ligand 2 (CCL2), draw Tregs to the surrounding tumor milieu." (PMID 39452154, 2024). "In particular, the CCL2/CCR2 axis has been well documented to mediate Treg recruitment and accumulation across gliomas and diverse types of tumors." (PMID 39034411, 2024). "CCL2, acting through pathways like PI3K/AKT and JAK/STAT, is crucial for macrophage and glioma cell migration, making it a potential target for tumor microenvironment modulation." (PMID 38594692, 2024). "In the glioma microenvironment, microglia can be recruited by gliomas through chemoattractants such as CCL5, CCL2, CX3CL1, and CXCL12, and can penetrate the tumor." (PMID 38549161, 2024). "DAMPs induces microglia in the area surrounding tumor necrosis to express IL-1β in a TLR-mediated manner, which induces glioma cells to release a range of cytokines such as CXCL8,CCL2, IL-1β and IL-6." (PMID 37700840, 2023). "Three Gene Expression Omnibus datasets were analyzed and revealed that IL‐1β levels were positively correlated with PD‐L1 and CCL2 expression in ovarian cancer, NSCLC, and glioma." (PMID 37009412, 2023). "These cells are recruited to the TME by the secretion of chemokines such as CCL2 and CXCL12 by glioma cells." (PMID 37686020, 2023). "This suppressive action is carried out by TGF-β, IL-10 cytokine, and CCL2 (MCP-1), which are released by the glioma and microenvironmental cells, which recruits Tregs, MDSC, and TAMs infiltrating the tumor disrupting lymphocyte function." (PMID 37165457, 2023). "Chemoattractants such as MCP-1 (CCL2), MCP-3 (CCL7), SDF-1 (CXCL12), CX3CL1, POSTN, GM-CSF, M-CSF (CSF-1) and EGF produced by glioma cells actively recruit TAMs and thus promote tumor growth." (PMID 37705736, 2023). "Several factors, including STI1, EGF, CSF-1, CCL2, IL-6, TGF-β and TGF-β2, are released from TAMs and can promote glioma proliferation and/or migration." (PMID 37705736, 2023). "This activates the p38 MAPK pathway, upregulation of CCL2 expression, and enhancement of the tumor stem cell (GSC) phenotype, promoting glioma progression." (PMID 37700840, 2023).
glioma (continued). "In vitro, CCLs such as CCL2 and CCL5 exhibited a meaningful effect on the attraction and migration of glial tumor cells." (PMID 36980182, 2023). "Chemokines and paired receptors, including CCL2 and CCR2, were upregulated in TANK-expressing gliomas." (PMID 37215097, 2023). "To further validate our findings, we performed IHC and multiple immunofluorescences staining on two of the TAM markers and found that the expression of BCL2A1 was significantly correlated with CCL2 and CD68, and they were coexpressed in gliomas." (PMID 37889551, 2023). "Monocyte chemoattractant protein-2 (CCL2, or MCP-1), the first identified chemoattractant molecule, is a critical molecule that recruits resident microglial cells to glioma and promotes its progression." (PMID 37012233, 2023). "Survival analysis using our own glioma tissue microarray and four GBM databases consistently showed that LIF and CCL2 predicted poor survival of GBM patients." (PMID 34987659, 2022). "While CCL2 levels were similar for glioma cells co-culture with WT or CD44-/- microglia, IL-6 mRNA levels were reduced by half in glioma cells co-cultured with CD44-/- microglia, compared to WT." (PMID 35992852, 2022). "In this study, we identified that SU4312 exhibits an anti-glioma effect by down-regulating YAP and CCL2, improving the tumor immune microenvironment." (PMID 36013004, 2022). "In glioma, BMDMs and microglia accumulate in tumor tissue attracted by chemokines, such as CSF1 and CCL2, secreted by tumor cells and constitute the glioma-associated macrophages/microglia (GAM)." (PMID 35494072, 2022). "CC motif chemokine ligand 2 (CCL-2), also known as monocyte chemoattractant protein 1 (MCP-1), is a major chemokine that acts as a glioma cell-derived monocyte chemotactic factor." (PMID 35741603, 2022). "Survival of C57BL/6 mice orthotopically implanted with KR158B, KR158B CCL2 KD, and KR158B CCL7 KD glioma cells were also assessed." (PMID 36685592, 2022). "Glial cells appear to be the primary source of CCL2, and supplementing GSCs with CCL2 alone reproduced some effects of the TME on glioma invasion and stemness." (PMID 35906273, 2022). "In conclusion, our results suggest that SU4312 represses glioma progression by down-regulating YAP transcription and consequently CCL2 secretion." (PMID 36013004, 2022). "To test the concept that CCL2 and CCL7 drive the recruitment of CCR2+/CX3CR1+ cells into the glioma microenvironment, we took a combinatorial targeting approach in vivo." (PMID 36685592, 2022). "In this glioma–TIM crosstalk, glioma cells produce cytokines, such as CCL2, GM-CSF, and IL-6, that promote chemoattraction, recruitment, and maturation of myeloid cells in the tumor microenvironment." (PMID 35884700, 2022). "In CCL2-null mice, the number of MDSCs is decreased, but CD8+ T cells are increased, which attenuates the progression of BRAFi-resistant gliomas." (PMID 36077785, 2022). "We then performed IHC on a tissue microarray containing 169 glioma cases to evaluate the prognostic significance of LIF and CCL2." (PMID 34987659, 2022). "CCL2, also known as monocyte chemoattractant protein-1 (MCP-1), was originally obtained in 1989 from the culture supernatant of human glioma cells and human blood mononuclear leukocytes." (PMID 36110847, 2022). "Microglia and macrophages are vigorously triggered by the glioma via the expression of chemoattractants such as monocyte chemoattractant protein (MCP-1, also known as CCL2), stromal-derived factor-1 (SDF-1), and macrophage-colony stimulating factor (M-CSF)." (PMID 35419058, 2022). "In glioblastoma, CSCs generate higher levels of the chemoattractants C-C motif chemokine ligand 2 (CCL2), CCL5, vascular endothelial growth factor-A (VEGF-A), and neurotensin than the bulk of the glioma." (PMID 34235155, 2021). "Monocyte chemotactic protein 1 (MCP-1, CCL2) secreted by glioma cells mediated the recruitment of CCR2+ monocytes and macrophages, and CX3CL1 induced the infiltration of CX3CR+ microglia." (PMID 34211978, 2021).
glioma (continued). "GAMs produce CCL2, a chemokine recruiting CCR4+ Treg and CCR2+Ly-6C+ monocytic MDSCs in murine gliomas." (PMID 34504786, 2021). "Several chemokines and cytokines, including CCL2 and CX3CL1, are responsible for GAMs recruitments and expansion in glioma." (PMID 34084145, 2021). "Glioma tumor cells release CCL20 and induce CCL2 production in TAMs and GAMs attracting MDSCs into TME." (PMID 33919732, 2021). "Treatment of tumor-bearing mice with acetylsalicylic acid (ASA) delayed glioma development and reduced MDSC-attracting chemokine CCL2 in the TME." (PMID 34439380, 2021). "TCGA database chemokine analysis showed that CXCL16 and CCL2 were significantly expressed in GBM tissue compared with WHO grade II and grade III glioma." (PMID 34638384, 2021). "We found that the following neutrophil chemokines—MMP9, CCL2, CCL5, CXCR4, CXCR2, CCL23, and IL8 (p = 0.07)—were enriched in TERTmut gliomas (t-test, p < 0.05)." (PMID 33996815, 2021). "Immunoregulatory cytokines such as pro-inflammatory factors (IL-1, IL-2, TNF-α, IFN-γ), anti-inflammatory factors (IL-10, TGF-β), and chemokines (CCL-2, CCL-5, CCL-7, CX3CL1) are synthesized and secreted in the microenvironment of glioma." (PMID 34630121, 2021). "Systemic CCL2 blockade with anti-CCL2 antibodies (Ab) resulted in decreased TAMs and MDSCs as well as modestly prolonged survival both in mice bearing intracranial GL261 glioma or intracranial human U87 glioma xenografts." (PMID 33540898, 2021). "The CCL2/CCR2 signaling is reported to be crucial for the development of TAMs and promotion of tumor growth in a rat glioma model." (PMID 32596397, 2020). "CCL2 expression pattern was very similar to that of CCRL2, and significantly increased with higher glioma tumor grade, whereas CCL5 expression exhibited an inverse relationship and its level decreased with increasing tumor grade." (PMID 32456359, 2020). "Since it is well known that CXCL12 activates members of the MAP kinase family in gliomas via its G-protein-coupled receptors CXCR4 and CXCR7, it seems obvious that CXCL12 regulated CCL2 and SAA2 expression during cellular dormancy entry via these pathways." (PMID 32346064, 2020). "On the other hand, an increased expression of CCL2 and CCL7 has shown anti-tumor effects in cervical carcinoma, glioma and mastocytoma induced by gene therapy in laboratory animals." (PMID 33182504, 2020). "Previous study reported that glioma cells may recruit neighboring microglia by secreting low levels of CCL2 and enhance the amplified release of CCL2 in microglia cells, which lead to recruiting more microglial cells into the tumor site to promote the progression and development of glioma." (PMID 31183364, 2019). "Whether CCL22 and/or CCL2 are significant Treg chemotactic factors in vivo is still a matter of contention; however, it is evident that other soluble factors within the glioma microenvironment also contribute to Treg chemotaxis, and these factors remain to be identified." (PMID 26217588, 2015). "For example, various murine glioma models have shown that depletion of MDSCs, either via COX-2 inhibition, antibody-mediated MDSC depletion, or CCL2 neutralization, can prolong the survival." (PMID 26217588, 2015). "This overexpression of IL1β in turn promotes glioma growth, induces activation of the p38 MAPK pathway, increases the GSC phenotype, and upregulates CCL2 expression, which correlates with greater monocyte infiltration." (PMID 25987130, 2015). "Yi and colleagues found that glioma-initiating cells produced CCL2, CCL5, VEGF-A, and neurotensin at higher levels than the glioma cells; these findings suggest that CSCs play an important role in TAM recruitment by secreting macrophage chemoattractants." (PMID 25125485, 2014). "This normal microglia produced NO in turn stimulated co-cultured glioma cells' migration and their synthesis of tumor necrosis factor-alpha (TNF-alpha) and macrophage chemotactic protein-1 (synonymous with CCL2, MCP-1)." (PMID 25211298, 2014).
glioma (continued). "In our preclinical study, neutralizing mAb against CCL2, a chemokine with MDSC attracting properties, reduced MDSC infiltration into gliomas in mice." (PMID 24202450, 2013). "Notably, antibody-mediated targeting of the Treg CCL2 high-affinity receptor, CCR4, reduced intertumoral Treg abundance and prolonged survival in a mouse glioma model." (PMID 39046599, 2024). "mRNA levels of CCL2 were not significantly different when glioma cells were co-cultured with CD4 + helper T cells." (PMID 39046599, 2024). "Regarding CCL2, increased expression correlates with higher risk in kidney renal papillary cell carcinoma (KIRP) and low-grade glioma (LGG), indicating its role as a negative prognostic marker for these malignancies." (PMID 39635438, 2024). "Our data indicate that targeting either CCL2 or CCR4, alone or in combination, may represent a viable therapeutic strategy to diminish Treg accumulation in the glioma microenvironment." (PMID 39046599, 2024). "Gliomas help recruit TAMs to the TME by secreting various chemokines, including monocyte chemoattractant proteins (MCP-1/CCL2 and MCP-3), C-X-C motif chemokine 12 (CXCL12), colony-stimulating factor 1 (CSF-1), lysyl oxidase (LOX), and glial cell-derived neurotrophic factor (GDNF)." (PMID 38254796, 2024). "Non-neoplastic astrocytes also contribute to glioma progression by expressing tumor-promoting proteins such as TGF-ß, STAT3, CCL2 and CSF1 in later tumor stages after causing initial astrogliosis at the tumor boundary in earlier tumor stages." (PMID 38275375, 2023). "has found that gliomas cell lines GPL261 and U87 can secret abundant CCL2 in vitro." (PMID 36761752, 2023). "In glioma, MDSCs are expanded and recruited by a variety of inflammatory cytokines and chemokines secreted by glioma cells and other immune cells, such as GM-CSF, S100A8/9, prostaglandin-E2 (PGE2), CCL2 and IL-8." (PMID 37234776, 2023). "Taken together, the upregulation of CCL2 and GM-CSF in regrown tumors detected in our study suggests increased TIM infiltration and proliferation in relapsed tumors, an immunosuppressive shift in the tumor microenvironment, and enhanced glioma cell motility." (PMID 35884700, 2022). "Glioma-derived cytokines are the primary stimuli that induce the recruitment and proliferation of MDSCs, which can be MDSCs recruiters (including CCL2, CXCL8, SDF-1, and CCL2) and/or MDSCs expanders (including IL-6, PGE2, IL-10, VEGF, and GM-CSF)." (PMID 36276147, 2022). "Overall, SU4312 may inhibit CCL2 expression by down-regulating YAP, thereby promoting anti-tumor immunity and inhibiting glioma progression." (PMID 36013004, 2022). "Interestingly, the glioma TME-generated CCL2 mediates the recruitment of inhibitory CCR2+ monocyte MDSCs and Tregs, while mIDH glioma has a reduced CCL2 expression." (PMID 36186781, 2022). "The authors also showed that in the absence of CCL2, Tregs failed to accumulate in the GBM TME and that CCR4-deficient mice were defective in glioma accumulation." (PMID 36338705, 2022). "Additionally, CCL2 blockade reduced GAMs infiltration and prolonged the survival of C57BL/6 mice bearing GL261 glioma." (PMID 35985661, 2022). "CCL2 recruits immunosuppressive regulatory T cells that express CCR4 to induce Tregs migration to glioma tissue for immune evasion, which is the main sign of tumorigenesis and a powerful obstacle to effective cancer treatment in gliomas." (PMID 36419652, 2022). "CCL2 and CCL7 are produced, at least in part, by glioma cells and our study indicates that CCL2 and CCL7 function in a redundant manner to induce the migration of CCR2+/CX3CR1+ M-MDSCs into the glioma microenvironment." (PMID 36685592, 2022). "We found that SU4312 hindered glioma progression by down-regulating YAP and its target gene CCL2." (PMID 36013004, 2022). "The following phenotype detection comparing proliferation, apoptosis, and migration of glioma cells with or without CCL2 knockdown further verifies the inhibitory role of CCL2 in glioma." (PMID 33414423, 2021).
glioma (continued). "In this study, CCL2, CCL5, CXCR4, MMP9, and CXCR2 expression was found to be high in TERTmut glioma from all samples and IDHwt subgroups with high levels of neutrophil infiltration, which indicated that N2 phenotype neutrophils were associated with TERT mutation." (PMID 33996815, 2021). "To investigate whether CYB561D2-activated STAT3 induces the expression of immunosuppressive genes in gliomas, we measured protein expression of FASLG, TGF-β2, CD70, PD-L1, PD-L2, CCL2 and TDO2 in U251 and U87 transfected with CYB561D2 plasmid for 48 h." (PMID 34372858, 2021). "In addition to CCL2, the macrophage inhibitory factor (MIF) is secreted by glioma cells and regulates MDSCs recruitment into TME." (PMID 33919732, 2021). "Finally, immunohistochemistry (IHC) assays were conducted to explore the expression of FCGBP, PD-L1, CCL2 and CD8 in glioma and correlations between them." (PMID 35047393, 2021). "In GSCs, celecoxib revealed significant decrease in mRNA levels of Ccl2 and Cxcr3 but not of Ccr2 and Cxcl10, which was consistent with the high mRNA levels of Ccl2 in the glioma model and GSCs but none of Cxcl10 in GSCs." (PMID 32943658, 2020). "We newly found that in the mouse glioma model, celecoxib decreased mRNA levels of Ccl2, CxcL10 and Cxcr3 but not of Ccr2 and protein expression of CCL2 and CXCL10 in the tumor and peri-tumor." (PMID 32943658, 2020). "Gl261 tumors grown in CCL2-deficient mice or mice treated with a small-molecule antagonist of CCL-2 receptor, CCR4, failed to maximally accumulate Tregs and M-MDSCs within the glioma microenvironment." (PMID 32240177, 2020). "We analyzed SIRT1, CCL2, VCAM-1 and ICAM-1 in human glioma cell lines by immunoblotting." (PMID 31207928, 2019). "CCL2 (also known as MCP-1), a chemokine that attracts macrophages, is consistently overexpressed in a number of glioma cell lines and in some human high grade gliomas with MG infiltration." (PMID 26124920, 2015). "CCL2/MCP1 has been shown to be protumorigenic and a target for therapy in glioma and other cancers." (PMID 23646114, 2013). "Targeting myeloid cells by disrupting the CCL2/CCR2 axis, which regulates monocyte and macrophage recruitment to the tumor microenvironment, can limit the infiltration of pro-tumorigenic myeloid cells and enhance anti-tumor immune responses in experimental gliomas." (PMID 40281508, 2025). "Moreover, canine glioma cells increased CCL2 mRNA expression when exposed to Tregs but not CD4 + helper T-cells." (PMID 39046599, 2024). "TAMs produce many proteins that can enhance glioma proliferation and/or migration, such as stress-inducible protein 1 (STI1), epidermal growth factor (EGF), colony-stimulating factor 1 (CSF-1), chemokine ligand 2 (CCL2), interleukin-6 (IL-6), and transforming growth factors: TGF-β and -β2." (PMID 39452154, 2024). "CCL2, referred to as MCP-1 (Monocyte chemotactic protein-1), is secreted by glioma cells and binds to CCR2 expressed on microglia, inducing microglia to recruit to the glioma region and release interleukin-6 (IL-6) thereby promoting the invasion and growth of glioma cells." (PMID 37700840, 2023). "M2 macrophages may promote tumor progression and poor prognosis by inhibiting CD8+ T cell function.Numerous studies have shown that various chemokines, including CCL2, CXCL12, LOX, MCP-3, and M-CSF, are secreted by glioma cells to attract M2 macrophages and change their phenotypes." (PMID 37766864, 2023). "However, glioma cell line expresses MCP-3/CCR7 instead of MCP-1/CCL2; moreover, MCP-3 but not MCP-1 level corelated with the number of tumor-infiltrating macrophage in tissues from human patients." (PMID 32596397, 2020). "Importantly, CCL2 then recruits regulatory T cells (Tregs) and myeloid-derived suppressor cells (MDSCs) through CCR4 and CCR2 as significant contributors to the potently immunosuppressive glioma microenvironment." (PMID 32296458, 2020).